FAM131B (family with sequence similarity 131 member B)
Synonyms: KIAA0773
Tractability: PROTAC: its protein half-life has been measured.
Gene: Protein-coding gene on chromosome 7 (143,353,400 to 143,362,815, reverse strand). Ensembl gene ENSG00000159784.
Subcellular location (Human Protein Atlas): Nucleoplasm; Cytosol
Pathways (Reactome):
Disease: Signaling by BRAF and RAF1 fusions
Gene Ontology:
Molecular function: protein binding
Cellular component: cytosol; nucleoplasm
Genetic constraint (gnomAD): Loss-of-function variants: 19 observed, 39.73 expected, observed/expected ratio (o/e) 0.48, 90% interval 0.33 to 0.7. The upper end of that interval is the gene's LOEUF score, 0.7, which puts it in group 2 of 6, group 1 being the genes least tolerant of losing a copy. Missense variants: 364 observed, 476.72 expected, observed/expected ratio (o/e) 0.76, 90% interval 0.7 to 0.83. Synonymous variants: 179 observed, 182.22 expected, observed/expected ratio (o/e) 0.98, 90% interval 0.87 to 1.11.
Homologues: Orthologues: chimpanzee FAM131B (99% identical), pig FAM131B (97% identical), macaque FAM131B (97% identical), rat Fam131b (96% identical), mouse Fam131b (96% identical), dog FAM131B (95% identical), rabbit FAM131B (94% identical), guinea pig FAM131B (94% identical), zebrafish fam131ba (44% identical), zebrafish fam131bb (44% identical). Paralogues in human: FAM131A (32% identical), FAM131C (24% identical).
Diseases named in the same sentence as FAM131B in open-access papers:
FAM131B is named in the same sentence as 5 diseases in open-access papers, as found by Europe PMC text mining. Sharing a sentence is not in itself a finding about the gene and the disease. The quoted sentences say what the papers report.
ganglioglioma (1 paper, 2018). A well differentiated, slow growing neuroepithelial neoplasm composed of neoplastic, mature ganglion cells and neoplastic glial cells. "For example, BRAF p.V600E has been observed in 25%–35% of adult and pediatric gangliogliomas, whereas other BRAF genetic alterations and KIAA1549-BRAF and FAM131B-BRAF fusions have also been observed in low-grade gliomas, the former fusion having been identified in gangliogliomas." (PMID 29434027, 2018).
FAM131B also shares sentences with these, for which no sentence is quoted: epilepsy (1 paper); glioma (1); low grade glioma (1); prostate carcinoma (1).